CD34 (CD34 molecule)
Diseases named in the same sentence as CD34 in open-access papers (continued):
Sharing a sentence is not in itself a finding about the gene and the disease.
tumor (continued). "Using marker-based method, we found here that ESCC tumor burden in vivo could increase the HSC-derived CAF progenitors in BM (defined as FGFR2+CD34+CD45+ cells) and HSC-derived CAF precursors in peripheral circulation (defined as FGFR2+CD34+CD45+Col I+ cells)." (PMID 35941662, 2022). "Immunohistochemistry showed that the tumor cells had focal membranous expression of CD99, nuclear/cytoplasmic expression of B-cell lymphoma 2, and cytoplasmic/membranous expression of smooth muscle actin and CD34, consistent with an intermediate-grade spindle cell sarcoma." (PMID 35797605, 2022). "Indeed, in multiple processes, including repair, tumor stroma formation, diabetes, fibrosis and systemic sclerosis, the presence or absence of CD34+SCs/TCs plays an important role." (PMID 36012273, 2022). "Multivariate binary logistic regression analysis finally included the tumor type (GG vs. DNT, P < 0.001; OR 13.3, 95% CI 5.9–29.9) and the patient population (adults vs. children, P = 0.014; OR = 2.5, 95% CI 1.2–5.2) into the predicting model of GNT with CD34 positive expression." (PMID 36307486, 2022). "Statistical analyses revealed a positive correlation between α-SMA and endothelial antigens CD34, suggesting that CAFs and NPC tumor cells may enhance neoangiogenesis in a VEGF- and SDF-1-dependent manner by the recruitment endothelial progenitor cells from the bone marrow into the tumor stroma." (PMID 35311066, 2022). "Moreover, CD34/PAS staining indicated that EXO-miR-125a treatment hampered the VM formation abilities, and TUNEL assay demonstrated that EXO-miR-125a enhanced the level of apoptosis of tumor cells." (PMID 35251967, 2022). "Immunostaining demonstrated that the tumor cells were negative for c-kit, CD34, PDGFRα, and DOG-1." (PMID 34526110, 2021). "The BMDCs recruited by the tumor include CD133+/CD34+/VEGFR-2+ bone-marrow-derived endothelial progenitor cells (EPCs), which undergo differentiation and incorporation into newly formed blood vessels, where they stimulate tumor vascularization as a result of paracrine signaling." (PMID 34771577, 2021). "Immunohistochemically, tumor cells were positive for vimentin, CD34, but were negative for S-100." (PMID 34909162, 2021). "Interestingly, the main cell type observed in the nonimmune compartment seven weeks after tumor induction, when tumor masses were fully developed, was a fibro/adipogenic-like population characterized by the expression of the Sca1, CD90.2, Vimentin, CD140α and CD34 markers." (PMID 33671425, 2021). "Finally, low mitotic count, lack of CD34 expression, tumor necrosis and intranuclear cytoplasmic pseudoinclusion can immediately exclude undifferentiated pleomorphic sarcoma." (PMID 33916538, 2021). "Interestingly, these tumor cells were negative for CD34 and only occasionally showed S100 protein positivity." (PMID 33803146, 2021). "Immunohistochemical staining revealed the tumor cells to be positive moderately and diffusely for CD34 and focally for SMA and negative for Cam5.2, epithelial membrane antigen (EMA), desmin, calponin, TLE-1, CD99, Stat6, anaplastic lymphoma kinase (ALK, 1A4), SOX10, and S100 protein." (PMID 34256767, 2021). "In contrast to that in C-DFSP, the expression of CD34 in FS-DFSP tumor tissues is negative." (PMID 33499900, 2021). "Focal staining with CD34 was observed, whereas the tumor was negative for S100 and SOX10." (PMID 32860002, 2021). "However, these compounds also affect normal hematopoiesis, interfering with self-renewal and differentiation of CD34+-Hematopoietic Stem/Progenitor Cells (HSPC), and, in turn, could modulate the generation of potential anti-tumor effector lymphocytes." (PMID 33467134, 2021). "The CD34 was positive in all 29 pathological samples in our research, whether the tumor recurred or not." (PMID 33499815, 2021).
tumor (continued). "In addition, treating this mixture of immune cells with the immune checkpoint inhibitors (anti-CTLA4 and anti-PD1), which allow for downregulation of Tregs, proper activation of CTL, Th, and memory T cells, with subsequent suppression of tumor cells through downregulation of CD133, CD34, and CD44." (PMID 37305162, 2021). "However, the absence of CD34+ fibroblasts in the tumor stroma statistically significantly correlated with the presence of αSMA+ myofibroblasts in the tumor stroma, both in the semiquantitative and the dichotomized analyses." (PMID 32435886, 2020). "Indeed, in a review of 150 cases, 90% of tumours were positive for CD117 and 50% for CD34." (PMID 32560571, 2020). "Additionally, CD34-sorted cells elevate the tumour initiating ability of cancer cells compared to non-sorted cells." (PMID 33123267, 2020). "Notably, D2 and NANOG are specifically expressed in CD34-negative cells (in the bulk of the tumor) and not in the cancer stem cell population." (PMID 32197405, 2020). "However, the model with CD34+ cells resulted in lower number of metastases to hTEB and overall lower tumor burden to hTEB compared to a model with no prior injection of CD34+ cells." (PMID 32570871, 2020). "In our own experience with more than 280 DNT, all of which can be classified as classic variants with nodular growth, a specific glio-neuronal element and no tumor-cell related CD34-immunoreactivity, we have not observed a single patient with tumor relapse due to malignant progression." (PMID 32151273, 2020). "The tumor cells expressed immunoreactivity for vimentin, but not for S100, CD34, actin, or desmin." (PMID 32605652, 2020). "Also MVD, as determined by CD34 antibody, was not correlated with tumour grade and pT stage and appeared to be non useful prognostic factor for patients’ BRFS as shown in some earlier study." (PMID 30989489, 2020). "However, high α6β1-integrin expression promotes tumour-initiating abilities regardless of CD34 enrichment status." (PMID 33123267, 2020). "However, both AML and MDS are heterogeneous diseases, and DLX5 methylation pattern were not analyzed in single tumor cell population such as CD34+ cell population, leading to a huge difference of DLX5 methylation in patients with AML and MDS." (PMID 32508046, 2020). "However, recent results in dogs demonstrated a different cytokeratin (CK) and stem cell marker expression pattern profile in the two tumours: the basal cell markers p63 and CK14 were diffusely expressed in BCC, while TB tumours were strongly positive for CK8 and CD34, CK15 and CK19." (PMID 32397255, 2020). "Hence, CD34 and VWF upregulation could be involved in abnormal vasculogenesis during tumor regrowth." (PMID 31803626, 2019). "The tumor cells were diffusely positive for CD34, STAT-6 and FLI-1, and negative for pan-cytokeratin, CAM5.2, p63, S100 protein, CD31, SMA, and calponin.ERG and Ki67 immunostaining showed an accentuated nuclear staining pattern in the central dedifferentiated area." (PMID 30777087, 2019). "In the saline group, CD34-positive tumor vessels did not infiltrate the necrotic area." (PMID 31336612, 2019). "Compared to the vehicle group, MLN0128 or PD901 monotherapy as well as combination treatment group led to a slight decrease of CD34 immunoreactivity, indicating that inhibition of angiogenesis is not a major mechanism for the anti-tumor activities exerted by MLN0128 or PD901 in AKT/c-MET mice." (PMID 31277283, 2019). "There was no expression of CD34 by the tumour cells (not shown)." (PMID 31221668, 2019). "Immunohistochemically, the tumor cells were negative for CD34 but positive for STAT6 and vimentin." (PMID 31020464, 2019). "Currently, neither endoglin nor CD34 expression adequately reflects true MVD values in tumor tissues, and the use of Abs to both antigens may be necessary to achieve realistic results." (PMID 29748768, 2018).
tumor (continued). "CD34 expression was markedly reduced in AMPK knockdown tumor, which could be rescued by Skp2 S256D, but not Skp2 S256A." (PMID 30413706, 2018). "Immunohistochemically, the tumor cells are negative for CD34, CD117, and S-100 protein." (PMID 30223791, 2018). "But in our case, tumor cells showed negative expression for CD34." (PMID 30253798, 2018). "The MIB-1 labeling index was < 5% and tumor cells were negative for CD34 and bcl-2." (PMID 29168109, 2018). "Also, 89 of 186 evaluable TMA cores exhibited more than 10 CD34+ vessels/core, while only 8 of 169 evaluable TMA cores had more than 10 VEGFR2+ vessels/core, implying that only a proportion of CD34+ tumor stromal vessels co-expressed VEGFR2 protein in their endothelial lining." (PMID 28533703, 2017). "Immunohistochemical staining for CD34 revealed that the treatment with anti-DLL4 mAb strikingly increased vessel branching in both EV- and mJAG1-tumours, suggesting a predominant role of DLL4 in the control of tumour angiogenesis and tumour growth in either EV-tumours or mJAG1-tumours." (PMID 28445154, 2017). "Biopsy of the nodule and atrophic plaque revealed dense proliferation of spindle-shaped tumor cells from the dermis to the subcutaneous adipose tissue, and positive immunostaining for CD34 and vimentin in addition to negative staining for factor XIIIa and α-smooth muscle actin." (PMID 26932148, 2016). "Therefore, net-like structures with PAS positive and CD34 negative staining were considered as positive VM formation in tumor tissues." (PMID 27793002, 2016). "These appear to originate from leptomeningeal-derived tumor cells, rather than vascular stroma, as no increased vascularity or vascular thrombosis was observed in these regions by immunohistochemistry for CD34 or factor VIII (endothelial), or CD61 (thrombocyte) antigens." (PMID 27255663, 2016). "Both tumors express, consistent with their glial lineage, the glial fibrillary acidic protein (GFAP), whereas other markers are reported to have distinct immunoreactivity, e.g. the endothelial marker CD34 is frequently expressed in tumor cells of PXA, respectively not in tumor cells of gcGBM." (PMID 27253461, 2016). "Immunohistochemical analysis of tumor cells indicated the following: HMB-45(+); vimentin(+); smooth muscle actin (SMA)(+); melan-A(+); CK(−); hepatocyte(−); Arg-1(−); GPC-3(−); CK7(−); CK19(−); CK20(−); S-100(−); CD34 blood vessel endothelium(+); and no exact tumor suppository." (PMID 26698563, 2015). "Thus, selection of tumour cells for the expression of the bulge SC marker CD34 did not accelerate the tumour-initiating potential." (PMID 25608467, 2015). "Our in vitro assays of tumor-primed NK cell alloreactivity to normal hemopoieitic stem cells in the preclinical phase and during this trial showed no lysis or suppression of normal CD34+ bone marrow cells." (PMID 26062124, 2015). "Similarly, in a case of a 9-month-old boy with mesenteric IMT, Buccoliero et al15 found that the tumor cells were positive for vimentin whereas negative for CD34 and S100 protein." (PMID 26496281, 2015). "To determine if endothelial cells (ECs) within the tumor mass were host- (murine) or biopsy- (human) derived, we used a human-specific CD34 antibody that did not mark ECs in normal murine pancreata, or in orthotopic tumors generated by intrapancreatic injection of human PCCs into athymic mice." (PMID 25762644, 2015). "Indeed, xenograft tumor cells invaded outward along murine blood vessels; immunohistochemical staining with anti-human CD34 antibody yielded no signals (D9)." (PMID 25879429, 2015).
tumor (continued). "Nevertheless we can confirm 6 of their identified genes (SPP1, TOP2A, AREG, EGR1, CD34, and IGF1) as well as one of the identified miRNAs (hsa-miR-101), that they found to be differentially expressed in lymph node metastases compared to primary tumours and to normal tissue." (PMID 26537449, 2015). "The tumor was positive for α-smooth muscle actin and vimentin but negative for CD34 and KIT." (PMID 26697255, 2015). "Immunohistochemically tumor cells usually express CD34 and vimentin but not EMA and S100." (PMID 26090247, 2015). "CD31 or CD34 stains highlighted the capillary network but not tumour cells." (PMID 26201545, 2015). "CD34 and D2-40 can be either positive or negative in both tumor types." (PMID 24986479, 2014). "The CD34 marker was also positive in vessels but negative in the tumor." (PMID 25408738, 2014). "In distinct contrast, a remarkable reduction in the expression of CD34 was observed in tumor sections in PNS-treated complex mice compared to that from the vehicle-treated complex mice, suggesting that PNS exert a significant antiangiogenic effect in growing tumor." (PMID 24903055, 2014). "It should however be noted that differences in CD34 staining may over or underestimate the vascularity due to tumor-specific alterations in the vascular bed such that not all of the endothethial cells may be appreciated." (PMID 24755315, 2014). "Finally, Martin-Padura and colleagues demonstrated significant enrichment of CD34+/CD45- stem cells in adipose tissue over that of the bone marrow and that adipose stem cells could enhance tumor vascularization and growth in human tumor xenografts in mice." (PMID 25047738, 2014). "Even so, the expression of the stemness-related marker CD34 is elevated in tumor-derived ECs, but not in that of repair blastemas, whereas the adhesion molecule CD54 was found to be elevated in ECs of benign and malignant proliferating tissues but not in non-proliferating normal tissues." (PMID 24632811, 2014). "Immunohistochemical staining revealed that the tumor was negative for c-kit but positive for CD34." (PMID 24575748, 2014). "Smooth muscle actin, S-100, and CD34 were not expressed by the tumor cells." (PMID 24410763, 2014). "The tumor partly showed negative CD34 and a 20% proliferative index." (PMID 24443842, 2014). "CD34 was also negative in the tumor cells, but highlighted endothelial cells in numerous vessels." (PMID 24396463, 2014). "Most markers used to investigate the effectiveness of anti-angiogenic therapies characterize terminal points of the treatment, such as microvascular density by immunohistochemistry (IHC) with anti-CD34 antibodies in tumor sections, thus no real time information of the efficacy response is available." (PMID 25384034, 2014). "The tumor cells expressed CD34 and CD31 but were negative for cytokeratin." (PMID 23607567, 2013). "In summary, the data presented provide evidence that it is possible to generate monocytes from BM haematopoietic CD34+ stem cells of cancer patients, which show the ability to effectively present TAA or HER-2/neu369–377 dominant peptide and to act as cytotoxic cells against tumour cells in vitro." (PMID 23180014, 2013). "However sensitivity of ALDH1 immunostaining was slightly better than CD34 (p = 0.07) especially for grade III HPC and could be especially useful in this category of tumours." (PMID 24252471, 2013). "However, at recurrence the tumour showed ALDH1 and CD34 positivity." (PMID 24252471, 2013). "Furthermore, the lack reaction of Syn, CgA, S-100, NSE, CD34, and Desmin supported the origin of tumor cells from pulmonary epithelium, rather than neuroendocrine, vascular-endothelium, or myoepithelium." (PMID 23587094, 2013). "In addition, CD34 is variably expressed in SFT/HPC with some tumours showing focal or weak positivity or being negative." (PMID 24252471, 2013).
tumor (continued). "In our study, we observed an association of Oct-4 expression in NSCLC specimens with some features of tumor-induced angiogenesis, but the investigation revealed no prominent linkage between Oct-4 expression and neovascularization (defined by CD34 and VEGF-A expression)." (PMID 22300949, 2012). "Interestingly CD34 negative or faintly stained host vessels at the tumor-host interface were seen to be co-opted by tumor cells." (PMID 23153292, 2012). "CD34 immunohistochemical staining, which detects vascular endothelial cells, indicated that over-expression of miR-34a also had a very significant negative impact on tumor vascularisation, or angiogenesis." (PMID 22662276, 2012). "This suggests that while CD34 ablation, specifically on non-hematopoietic cells, results in impaired tumor growth, CD34 expression on hematopoietic cells may also play a lesser role." (PMID 21494591, 2011). "However, the function of CD34 in the tumor-extrinsic microenvironment has not been thoroughly examined." (PMID 21494591, 2011). "In addition, these L50 tumours showed over-expression of collagen IV, and reduced laminin 332, VEGF and CD34 levels, which may have restricted cell adhesion and neoangiogenesis." (PMID 22107808, 2011). "Several quality measures were compared including median number of CD34+ cells/kg collected, median number of CFU-GM/kg, median hospital stay, incidence of infections, time to engraftment of granulocytes and platelets, and evidence of tumor mobilization by peripheral smear." (PMID 22190942, 2011). "On the other hand, the increased necrosis in the "Carb-free" fed tumors was not due to an effect of the diet on tumor vasculature, ER stress or autophagy since the tumor expression of CD34, phospho-eIF2α(Ser51) and p62 were not significantly different among the 4 groups." (PMID 22018000, 2011). "The tumor cells were positive for CD34, and negative for α-smooth muscle actin and desmin." (PMID 21143833, 2010). "Tumours with higher CD34 MVD may also have higher CD105+ MVD, however it does not necessarily follow that active angiogenesis takes place." (PMID 18612312, 2008). "Moreover, CDIM9 did not produce tumor endothelial cell damage based on equal CD34 vessel staining of CDIM9-treated tumor samples compared with PBS-treated tumor samples (data not shown)." (PMID 17764562, 2007). "In addition, it should be noted that our CD34-antibody, a pan-endothelial marker, used to highlight vasculature reveals mainly pre-existing mature vessels and not tumor-induced neovessels." (PMID 17067385, 2006). "In addition, our finding of the expression of CD34 in both normal and tumor tissue indicated that it is not a reliable marker for HCC." (PMID 16650286, 2006). "To evaluate whether quantifying mtDNAc in BMMCs accurately reflects levels in the leukemic stem/progenitor cell fraction rather than a signal from the tumor microenvironment, we isolated CD34+/CD117+ cells (enriched for leukemic stem-progenitor cells, LSPCs) and measured the mtDNAc by qPCR." (PMID 40653487, 2025). "Additionally, it may modulate the microenvironment, thereby promoting the onset and progression of cancer, indicating that a high expression of these two cellular senescence markers, CD34 and NOX4, in endothelial cells, could be potential markers for tumor development." (PMID 39859485, 2025). "Our attempts to develop a context dependent positive control based on edited CD34+ cells were not successful due to oncogene-induced senescence and the difficulty to generate tumor cells from primary human cells, a far from simple issue which may require multiple hits and million of cells." (PMID 39416278, 2024). "Similarly, our case showed focal positivity for both CD34 and S100, while additional immunoreactivity may be present but is less specific for this type of neoplasm (e.g., WT1, CD10, desmin, and smooth muscle actin; not shown)." (PMID 39582973, 2024).